BST2 (bone marrow stromal cell antigen 2)
Diseases named in the same sentence as BST2 in open-access papers (continued):
Sharing a sentence is not in itself a finding about the gene and the disease.
cervical cancer (9 papers, 2016 to 2024). A primary or metastatic malignant neoplasm involving the cervix. "In our research, we found that lncRNA FGD5-AS1, miR-129-5p, and BST2 were associated with macrophage polarization and cervical cancer." (PMID 34692852, 2021). "Loss of BST2 obviously repressed cervical cancer cell proliferation, migration, and invasion while triggering cell apoptosis." (PMID 34692852, 2021). "It was hypothesized that downregulation of FGD5-AS1 inhibited cervical cancer by inducing M2 tumor-associated macrophage polarization via targeting miR-129-5p and regulating BST2." (PMID 34692852, 2021). "During the development of cervical cancer, BST2 induced cervical cancer cell growth, suppressed apoptosis and induced M1 macrophage but not M2 macrophage polarization." (PMID 37143676, 2023). "To study the mechanisms of tumor-associated macrophage polarization in cervical cancer, we found that decreased expression of lncRNA FGD5-AS1 inhibited M2 macrophage polarization via modulating miR-129-5p and BST2." (PMID 34692852, 2021). "We observed that FGD5-AS1 directly targeted miR-129-5p to promote M2 macrophage polarization through inducing BST2 in cervical cancer." (PMID 34692852, 2021). "The activation of FGD5-AS1 can promote the progression of cervical cancer by regulating BST2 to inhibit macrophage M1 polarization." (PMID 34966747, 2021). "In summary, our data focused on the association between FGD5-AS1, miR-129-5p, and BST2 and demonstrated that FGD5-AS1 promoted M2 macrophage polarization through regulating miR-129-5p-mediated regulation of BST2 in cervical cancer." (PMID 34692852, 2021). "Bone marrow stromal cell antigen 2 (BST2) can play critical roles in immune response, and the roles of BST2 in cervical cancer was explored currently." (PMID 34692852, 2021). "In conclusion, FGD5-AS1 induced M2 macrophage polarization via sponging miR-129-5p and modulating BST2, thus contributing to cervical cancer development." (PMID 34692852, 2021). "In lupus, an autoimmune disease 173 and cervical cancer 124, BST‐2 is hypomethylated and BST‐2 expression is significantly elevated in comparison to control specimens." (PMID 27042298, 2016). "In addition, FGD5-AS1-regulated BST2 plays a role in promoting M2 macrophage polarization and inhibiting M1 macrophage polarization in cervical cancer." (PMID 37628967, 2023). "An increase in BST2 has been reported in several types of cancer including cervical cancer." (PMID 36016386, 2022). "In our study, BST2 expression was significantly elevated in cervical cancer cells." (PMID 34692852, 2021). "The level of FGD5-AS1 and BST2 was detected by qRT-PCR in cervical cancer cells." (PMID 34692852, 2021). "In order to verify whether BST2 participate in cervical cancer progression via regulating M2 macrophage polarization in cervical cancer cells, SiHa cells were transfected with BST2 shRNA." (PMID 34692852, 2021). "We implied the effect of BST2 in M2 macrophage polarization in cervical cancer." (PMID 34692852, 2021). "FGD5-AS1 and BST2 expression was significantly upregulated in cervical cancer cells." (PMID 34692852, 2021). "Our findings revealed FGD5-AS1/miR-129-5p/BST2 as a new potential target for cervical cancer." (PMID 34692852, 2021). "FGD5-AS1 and BST2 expression was obviously upregulated in cervical cancer cells." (PMID 34692852, 2021). "BST2 was predicted and confirmed as a target for miR-129-5p in cervical cancer." (PMID 34692852, 2021). "In cervical cancer, FGD5-AS1, via the miR-129-5p/bone marrow stromal cell antigen 2 (BST2) axis, promotes tumor growth and M2 polarization." (PMID 38473915, 2024). "In our future study, we will collect enough human cervical cancer tissues to detect FGD5-AS1, miR-129-5p, and BST2 expression." (PMID 34692852, 2021). "A previous study demonstrated that BST2 regulated by FGD5-AS1 could promote M2 macrophage polarization and inhibit M1 macrophage polarization in cervical cancer." (PMID 36594082, 2023).
cervical cancer (continued). "Furthermore, lack of BST2 depressed cervical cancer cell growth, while inducing apoptosis." (PMID 34692852, 2021).
gastric cancer (9 papers, 2018 to 2024). A primary or metastatic malignant neoplasm involving the stomach. "Regarding the hypomethylated candidate genes, overexpression of BST2 is associated with poor survival in patients with CRC as well as those with esophageal or gastric cancer." (PMID 30360391, 2018). "The regulation of NF-κB signaling and its downstream proteins by BST2 has also been implicated in the metastasis of tumor cells, as shown by the decreased migration observed when BST2 is downregulated in gastric cancer cells." (PMID 39796009, 2024). "BST2 has the potential to enhance the ability of cell proliferation, apoptosis and motility by activating the NF-κB signaling pathway in gastric cancer." (PMID 36594082, 2023). "BST2 was also a target gene of miRNA 760 and positively related to the progression of gastric cancer." (PMID 37143676, 2023). "In gastric cancer, BST2 exerted oncogenic effects by regulating proliferation, apoptosis, and migration." (PMID 37143676, 2023). "In addition, the analysis of immunotherapy indicated that BST2 showed an effective ability in predicting immunotherapy, especially in gastric cancer, which is relatively closer to CRC." (PMID 36594082, 2023). "Knocking down BST2 suppresses gastric cancer cell proliferation and promotes apoptosis." (PMID 35267998, 2022). "BST2 overexpression correlates with poor prognosis in CRC, stomach cancer, and oesophageal cancer." (PMID 35968507, 2022).
glioblastoma (9 papers, 2010 to 2026). The most malignant astrocytic tumor (WHO grade IV). "Elevated BST2 expression correlates with poor prognosis in glioblastoma, breast, nasopharyngeal, and pancreatic cancers, and it serves as a circulating biomarker within small extracellular vesicles." (PMID 41595667, 2026). "The migratory and invasive potential of BST2/DIRAS3 in glioblastoma has only been validated in vitro by our current studies; pertinent marker assays that target the tumor microenvironment are required." (PMID 40649981, 2025). "Indeed, BST-2 overexpression due to DNA hypomethylation has been reported for glioblastoma and lupus." (PMID 25860442, 2015). "For instance, elevated BST2 expression in glioblastoma multiforme (GBM) correlates with diminished tumor purity, poor prognosis, and altered immune infiltration, while in oral squamous cell carcinoma (OSCC), it promotes cellular migration and invasion via the AKT/ERK1/2-STAT1 signaling pathway." (PMID 41281378, 2025).
autoimmune disease (8 papers, 2013 to 2024). A disorder resulting from loss of function or tissue destruction of an organ or multiple organs, arising from humoral or cellular immune responses of the individual to their own tissue constituents. "Our results showed that Bst2+/− mice developed arthritis earlier and with greater severity than Bst2−/− mice, suggesting a role for Bst2 in promoting the development of autoimmune diseases." (PMID 39796009, 2024). "To investigate the role of Bst2 in the development of autoimmune diseases, we induced arthritis in mice by injecting chicken collagen." (PMID 39796009, 2024). "In conclusion, we have presented genetic data supporting a role of the retroviral restriction genes, TRIM5, TRIM22 and BST2 in the autoimmune disease multiple sclerosis." (PMID 24066097, 2013). "Conversely, we hypothesized that BST2 may influence the development of autoimmune diseases, given that these conditions also rely on autoantigen-specific T cell activation in the LNs." (PMID 39796009, 2024). "Despite its antiviral functions, BST2 may be involved in some disease manifestations, for example, cancer and autoimmune diseases." (PMID 36034815, 2022). "Our data suggest that targeting the intracellular domain of BST2 in IFN-mediated inflammatory and autoimmune disorders might attenuate disease by redirecting TH17 cell responses toward a non-pathogenic phenotype." (PMID 36456734, 2022).
endometrial cancer (8 papers, 2009 to 2024). Primary or metastatic malignant neoplasm involving the endometrium (mucous membrane that lines the endometrial cavity). "IHC was used to confirm the expression of BST2 in a cohort of 177 patients as a potential biomarker for endometrial cancer." (PMID 39194522, 2024). "BST2 was the protein that showed the most significant differences in expression between normal and endometrial cancer cells." (PMID 39194522, 2024). "Based on observation that increased BST2 activity was accompanying endometrial cancer, anti-BST2 mAb has been developed and proved to exert a significant anticancer effect in experiments on mouse model." (PMID 33537341, 2020). "The anti-BST2 antibody had a potent antitumor effect against endometrial cancer both in vitro and in vivo, indicating that anti-BST2 antibody might be a potential therapeutic strategy for endometrial cancer." (PMID 37033258, 2023). "Recently, up-regulation of BST2 mRNA was reported in endometrial cancer." (PMID 19338666, 2009). "The results showed that four hub genes, APOE, BGN, BST2, and C1QB, were abnormally differentially expressed in normal tissues and endometrial cancer." (PMID 39650066, 2024). "Additionally, mAb against BST‐2 induced ADCC and CDC in BST‐2 positive endometrial cancer cells in vitro and tumor growth inhibition was achieved in a xenograft model." (PMID 27042298, 2016).
lung carcinoma (8 papers, 2016 to 2025). "Similar to MM, anti‐BST‐2 mAb was used as treatment for lung cancer." (PMID 27042298, 2016). "Among them, CTNNB1, ZEB1, CDC42, HSP90AA1, BST2, PCNA, and E2F1 have all been shown to promote lung cancer progression, while SAMHD1, HRAS, and NQO1 serve as tumor suppressor genes." (PMID 28498804, 2017).
pancreatic cancer (8 papers, 2016 to 2026). "Notably, IHC analysis revealed that BST2 is highly expressed not only in cancer cells but also in nontumor stromal components, aligning with reports of BST2+ macrophages being associated with poor prognosis in pancreatic cancer and BST2 expression in other cell types like stem cells." (PMID 41281378, 2025). "Additionally, a recent study highlighted the role of ERK-CXCL7 signaling in IFNα-induced BST2+ TAMs, facilitating immunosuppression and tumor growth in pancreatic cancer." (PMID 40368902, 2025). "The multifaceted role of BST2 in oncogenesis is well documented across various malignancies, where it modulates processes such as the EMT, the acquisition of drug resistance in CAR T-cell therapies, and the function of tumor-associated macrophages in pancreatic cancer." (PMID 41281378, 2025). "BCAT1, along with bone marrow stromal antigen 2 (BST 2) and the tyrosine kinase MERTK, promotes cancer progression by regulating TAM 2 polarization, offering a potential target for pancreatic cancer treatment." (PMID 40438606, 2025).
lupus (7 papers, 2015 to 2026). "DNA methylation has been linked with the regulation of BST-2 expression particularly in cancer cells, and in lupus." (PMID 34025670, 2021). "Lupus patients had low methylation and high expression of interferon regulatory genes, including BST2, IFIT3, IFI44L, and IFIT1." (PMID 38753689, 2024). "Patients with lupus presented with BST-2 hypomethylation on probes 1 to 7 compared to the controls, pointing to a common mechanism of methylation-dependent BST-2 regulation." (PMID 25860442, 2015).
melanoma (7 papers, 2019 to 2024). A malignant, usually aggressive tumor composed of atypical, neoplastic melanocytes. "Another report has shown that BST2 was significantly correlated with the clinical outcome of melanoma patients and lowly expressed in a high-risk subgroup, which is consistent with our study." (PMID 36086707, 2022). "In short, BST2 is part of an anti-CTLA4 response in melanoma and CLIC2 is a favorable prognosis biomarker." (PMID 38269333, 2023). "By analyzing the TCGA genomics data of SEL1L3, HAPLN3, BST2, and IFITM1, we found that the gene alteration rates in melanoma were 10% for SEL1L3, 4% for HAPLN3, 0.8% for BST2, and 0.6% for IFITM1, and these alterations were not recurrent." (PMID 33753855, 2021). "The genes in this signature, SEL1L3, HAPLN3, BST2, and IFITM1, may be functionally involved in melanoma progression and immune response." (PMID 33753855, 2021).
oral squamous cell carcinoma (7 papers, 2020 to 2025). "BST2 can promote the metastasis, invasion, and proliferation of oral squamous cell carcinoma through the AKT/ERK1/2 signaling pathway." (PMID 39650066, 2024). "BST2 expression is specifically upregulated in oral squamous cell carcinoma and is responsible for drug resistance." (PMID 35968507, 2022). "In oral squamous cell carcinoma, high BST2 expression could induce gefitinib resistance by regulating the EGFR pathway." (PMID 36594082, 2023).
hepatocellular carcinoma (6 papers, 2012 to 2023). A malignant tumor that arises from hepatocytes. "The HPA database indicated that UBE2O exhibited protein expression patterns opposite those of IFIT3 in both liver tissue and hepatocellular carcinoma tissue, although its expression was positively correlated with that of BST2 and TRIM21." (PMID 38129382, 2023). "BST2 has been shown to activate EGFR and the initiation of downstream signaling pathways by regulating its association with lipid rafts in hepatocellular carcinoma and to be involved in resistance to tumor cell death and chemotherapy." (PMID 35865015, 2022). "RNAseq analysis identified a long non‐protein‐coding RNAs named BISPR (BST2 IFN‐stimulated positive regulator) as a positive regulator of BST‐2 in IFNα2‐treated hepatocellular carcinoma (Huh7) cells." (PMID 27042298, 2016). "The data presented above demonstrated that BST-2-induced HBV restriction in hepatoma and hepatic cells is weaker than that in 293T cells, indicating that HBV may counteract BST-2 in hepatocytes." (PMID 26119070, 2015). "Our study began with a test of endogenous BST-2 in non-hepatic and hepatoma cell lines." (PMID 26119070, 2015). "Based on our observation that BST-2 inhibits HIV-1 ΔVpu in HepG2 and HeLa cells, we found that HBV could promote HIV-1 ΔVpu virus release from BST-2-positive HepG2 hepatoma cells but not from non-hepatic HeLa cells." (PMID 26119070, 2015).
ovarian carcinoma (6 papers, 2015 to 2025). A malignant neoplasm originating from the surface ovarian epithelium. "Our investigation commenced with an initial screening of public databases, which identified BST2 as a gene with significant prognostic implications in ovarian cancer." (PMID 41281378, 2025). "The expression of BST2 is closely related to the formation of an antitumor immune microenvironment in ovarian cancer." (PMID 41281378, 2025). "The findings propose that BST2 acts as a pivotal facilitator in the progression of ovarian carcinoma." (PMID 41281378, 2025). "In conclusion, CFP1 promotes ovarian cancer cell proliferation and apoptosis by regulating the transcription of BST2, and the expression of CFP1 was affected by CRL4 ubiquitin ligase complex." (PMID 35864225, 2022). "Using mass spectrometry-based proteomics approach, BST2 has been repeatedly detected in the exosomal fractions purified from B cells, ovarian cancer cells, thymic tissues, and urine." (PMID 26494939, 2015). "In a most recent paper, CpG-binding protein CXXC Zinc Finger Protein 1 (CFP1) stimulated cell proliferation in an ovarian cancer cell line (A2780) by enhancing BST2 transcription, and BST2 inhibition could reduce cell proliferation." (PMID 41281378, 2025). "RNA-seq analysis of the CFP1-deleted ovarian cancer cells transcriptome showed that 703 genes were altered, and gene ontology analysis showed that many of these genes were associated with cell mitosis and cell cycle regulation, such as CREB5 and BST2." (PMID 35864225, 2022). "Moreover, CFP1 affects gene transcriptional activity by binding to the BST2 promoter region to regulate the proliferation, apoptosis, and other biological activities of ovarian cancer cells." (PMID 35864225, 2022). "Therefore, we inhibited BST2 transcription by siRNA in ovarian cancer cells." (PMID 35864225, 2022). "In addition, we verified in vivo that BST2 overexpression could promote the tumor-forming ability of CFP1-deleted ovarian cancer cells using nude mouse tumor-forming experiments." (PMID 35864225, 2022). "Reducing BST2 expression could significantly inhibit the proliferation of ovarian cancer cells." (PMID 35864225, 2022). "We then explored the molecular mechanism of CFP1-mediated bone marrow stromal antigen 2 (BST2) transcriptional activity and identified how CFP1 affects ovarian cancer cell transcriptome." (PMID 35864225, 2022). "Silencing of the CRL4 E3 ubiquitin ligase complex ROC1 and CUL4A genes by siRNA significantly decreased the expression of CFP1 and BST2, consistent with that observed after MLN4924 treatment of ovarian cancer cells." (PMID 35864225, 2022). "While the expression of NOG, S1PR1, BTG4, and CREB5 genes was significantly increased, that of RASSF9, DNMT1, BST2, and SETD1A genes was significantly decreased in CFP1-deleted A2780 and ES-2 ovarian cancer cells, based on qRT-PCR results." (PMID 35864225, 2022). "Cell counting kit 8 experimental results showed that BST2 overexpression could significantly promote the proliferation and cell death rescue of MLN4924-treated ovarian cancer cells." (PMID 35864225, 2022). "In summary, the CRL4 E3 ubiquitin ligase complex could inhibit ovarian cancer cell proliferation by affecting CFP1 protein expression, while both CFP1 and SETD1 affected BST2 transcription to regulate ovarian cancer cell proliferation, apoptosis, and clone formation." (PMID 35864225, 2022).
AIDS (5 papers, 2009 to 2016). A syndrome resulting from the acquired deficiency of cellular immunity caused by the human immunodeficiency virus (HIV). "The present study investigated the role of BST2 during the natural course of retroviral infection in the SIV/macaque model for AIDS." (PMID 26554913, 2015). "Therefore, further studies on the mechanism of BST-2 function will provide beneficial information leading to novel therapeutic strategies against several virus-induced diseases including AIDS." (PMID 19490609, 2009). "Since antiviral BST2 activity has been mainly confirmed by in vitro data, we investigated its role in vivo on the disease progression using the SIV/macaque model for AIDS." (PMID 26554913, 2015). "In this study, we investigated the role of BST2 in the SIV rhesus macaque model, which represents currently the best animal model to study HIV infection and AIDS pathogenesis." (PMID 26554913, 2015). "By detecting an association between elevated BST2 expression with plasma viral load and only low BST2 levels in LTNPs, our results indicate rather limited effects of BST2 in vivo on the disease outcome in the SIV macaque model for AIDS." (PMID 26554913, 2015). "While neuroinflammation is a cardinal feature of HAD, antiviral responses including induction of IFN-α, MX-1, PRKRA or BST-2 await clarification of their expression in HAD, although several studies indicate the IFN-α might be increased in the brains of HIV/AIDS patients." (PMID 21645334, 2011). "Considering the clear association between viral load and BST2 levels throughout the infection and the lower expression of BST2 in LTNPs as early as 2wpi, there is little evidence that BST2 has a positive effect on disease progression in the SIV model for AIDS." (PMID 26554913, 2015).